TNF (tumor necrosis factor)
Diseases named in the same sentence as TNF in open-access papers (continued):
Sharing a sentence is not in itself a finding about the gene and the disease.
Insulin resistance (continued). "Furthermore, the analysis of condition media showed the absence of insulin resistance and immune cell-attracting inflammatory markers, such as LTB4, STAT-6, IL-4 and TNF-α levels." (PMID 32235695, 2020). "Moreover, vitamin is a negative modulator of inflammatory cytokine such as TNF-α and IL6, which are closely related to insulin resistance." (PMID 33042976, 2020). "Intriguingly, high-glucose load failed to impair glucose tolerance and did not change the levels of plasma IL-6 and TNF-α in TLR4 knockout mice, which suggests a critical role of TLR4 in increase of IL-6 and TNF-α levels and glucose intolerance and insulin resistance induced by high-glucose load." (PMID 31138952, 2019). "Moreover, we did not assess insulin resistance markers, such as homeostasis model assessment of insulin resistance, and inflammatory markers (MIF, TNF-α, and IL-6)." (PMID 30563254, 2018). "Combined with our study it was supposed that the raised TNF-α levels are not an intrinsic characteristic of PCOS, but it may be involved in promoting insulin resistance and androgen excess of PCOS." (PMID 27764100, 2016). "Visceral adiposity has been complicated with negative effects including insulin resistance and the elevated production of pro-inflammatory molecules leptin (LEP), resistin, tumor necrosis factor-α (TNF-α), IL-6, hypoxia-inducible factor 1 (HIF-1) and adipocyte fatty-acid binding protein (A-FABP)." (PMID 27703473, 2016). "Moreover, those two meta-analysis did not report the relations between TNF-α levels and the characteristics of PCOS, such as body mass index (BMI), insulin resistance, and androgen status." (PMID 27764100, 2016). "On the other hand, mitogen-activated protein kinase (MAP3K) is up-regulated in adipose tissue of obese mice and patients and correlated with TNF-alpha expression, but according to our knowledge, there is no previous report on HCV infection or insulin resistance involving MAP3K." (PMID 23133528, 2012). "Additionally, compared to hs-CRP, TNF-α provides more mechanistic insights into the metabolic dysfunction seen in PCOS, whereas hs-CRP reflects generalized inflammation but does not directly influence insulin resistance and ovarian dysfunction as TNF-α does." (PMID 40385768, 2025). "Notably, deletion of the insulin receptor in myeloid cells reduces macrophage infiltration during HFD, decreases circulating levels of TNF-α and protects against HFD-induced insulin resistance, highlighting insulin’s potential negative role in innate immune responses during MetS." (PMID 39605858, 2024). "Therefore, a high TNF-α level is not an intrinsic characteristic of PCOS, but it may be involved in promoting insulin resistance and hyperandrogenism of PCOS." (PMID 27764100, 2016). "Furthermore, when obese adult women exercised on a bicycle ergometer for 30 minutes a day, five days a week at 70% V ̇O2 max for 12 weeks, decreases in blood concentrations of both TNF-α and soluble TNF receptor 2 were observed in both the women with insulin resistance and those without." (PMID 24369466, 2013). "Conversely, the interaction of anti-TNF treatment with the change in DAS28 had no significant impact on HOMA-IR (F test = 0.06, P = 0.810), suggesting that the effect of anti-TNF treatment on insulin resistance is not confounded by improvement in disease activity." (PMID 22691241, 2012). "Furthermore, in the women with insulin resistance, intake of MOJ for 4 weeks reduced the plasma VCAM-1 levels (554.99 ± 15.63 to 545.31 ± 14.65 ng·mL−1, p = 0.039) but the plasma levels of ICAM-1, C-reactive protein, TNF-α, IL-6, and IL-10 were not significantly altered." (PMID 37469434, 2023).
Sepsis (3,204 papers, 1992 to 2026). Sepsis is defined as life-threatening organ dysfunction caused by a dysregulated host response to infection. "IL‐10 helps prevent hyperactivation of the innate immune system by inhibiting the effects of cytokines such as TNF‐α, IL‐1β, and IL‐6, thereby reducing the risk of multiple organ failure, and mitigating complications related to sepsis." (PMID 41573125, 2026). "In the initial stage of sepsis, the release of a large number of pro-inflammatory cytokines including TNF-α and IL-1β are associated with intestinal barrier impairment." (PMID 40885907, 2025). "Studies have shown that elevated levels of IL-6 and TNF-α are strongly associated with poor outcomes in sepsis patients, highlighting their central role in the pathophysiology of the disease." (PMID 40563999, 2025). "It has been reported that MaR-1 influences TNF-α levels in sepsis and that low MaR-1 levels are associated with lower TNF-α concentrations." (PMID 41517447, 2025). "Persistent inflammation post-sepsis, characterized by the sustained release of pro-tumorigenic cytokines like IL-6 and TNF-α, fuels tumor growth and immune evasion, increasing the risk of recurrence." (PMID 40563999, 2025). "Crucially, lower levels of IFN-γ (OR = 1.314, P < .001) and TNF-α (OR = 1.320, P < .001) measured within 24 hours of sepsis diagnosis were associated with the occurrence of SAE during the ICU stay." (PMID 41189156, 2025). "This reduction reflects endotoxin tolerance (ET), indicating innate immune suppression, and shows promise for TNFα as an early diagnostic biomarker for sepsis and bacteremia." (PMID 40862819, 2025). "In this context, we also evaluated the effects of the recombinant β-defensins on the secretion of TNFα, a pro-inflammatory cytokine associated with the pathological effects of sepsis, induced by LPS in bovine whole blood cells." (PMID 40898303, 2025). "JKAP is also lower in sepsis patients and is inversely associated with levels of TNF-α, IL-1β, and IL-17 and disease severity-related scales." (PMID 41458980, 2025). "The importance of TNF-α can be explained by the fact that mutation of TLR-4 affects patients’ development of sepsis and its degree due to different responsiveness of lipopolysaccharide (LPS)." (PMID 41357527, 2025). "Arg1 inhibition in monocytes abolished the protective effects of exercise on reducing body temperature decline, weight loss, IL-1β and TNF-α levels and sepsis-induced myocardial injury." (PMID 41398160, 2025). "The overwhelming production of proinflammatory cytokines, such as interleukin (IL)-1β, IL-6, tumor necrosis factor (TNF)-α, as well as reactive oxygen species (ROS) is a hallmark of sepsis and sepsis-associated AKI." (PMID 40656894, 2025). "Sepsis is defined by the impairment of the immune system, which is closely linked to an overabundance of proinflammatory cytokines like TNF-α, IL-1β, and IL-6." (PMID 40144662, 2025). "Monocyte transfusion significantly alleviated the drop in body temperature and body weight, as well as reduced IL-1β and TNF-α production caused by sepsis." (PMID 41398160, 2025). "Our findings indicate that cp‐OLA@MΦ NPs effectively neutralized key pro‐inflammatory cytokines such as TNF‐α, IL‐1β, and IL‐6, all of which are closely associated with the pathophysiology of sepsis." (PMID 39836501, 2025). "Myocardial dysfunction involves inflammatory mediators such as TNF-α and IL-6, while sepsis-associated acute kidney injury (SA-AKI) arises from hypoperfusion and inflammation, heightening the risk of progression to chronic kidney disease." (PMID 40265185, 2025). "DEX reduces sepsis-induced AKI by decreasing TNF-α and MCP-1 and increasing BMP-7, which is associated with decreasing HDAC2 and HDAC5, as well as increasing acetyl histone H3." (PMID 40989844, 2025).
Sepsis (continued). "Sepsis-induced immunosuppression exhibits two hallmark features: impaired monocytic production of proinflammatory cytokines (particularly TNF-α) upon endotoxin challenge and diminished lymphocyte proliferative capacity." (PMID 41256846, 2025). "The concentration of TNF-α is associated with the severity of sepsis and prognosis; the higher the TNF-α level, the more critical the condition." (PMID 40529149, 2025). "Generalized estimating equations showed that DS and tumor necrosis factor-α (TNF-α) were independently associated with ARDS onset in sepsis patients, but their generalizability across ARDS subtypes warrants further validation." (PMID 40404729, 2025). "Sepsis is a critical illness caused by infection that leads to excessive activation of systemic inflammatory cytokines, such as TNF-α, IL-1β, and IL-6, inducing immune dysfunction and resulting in systemic organ failure." (PMID 40565375, 2025). "Our study found that in sepsis patients, increased urinary GAGs and plasma TNF-α levels were associated with subsequent ARDS development." (PMID 40404729, 2025). "In LPS-induced sepsis mice, stefin B-deficient mice exhibited increased IL-1β secretion and TNF-α release was only significantly elevated at the 2-hour time point." (PMID 41017465, 2025). "Since excessive inflammation plays a vital role in the pathogenesis of sepsis-associated cardiac abnormalities, we measured the levels of inflammatory cytokines TNF-α and IL-1β." (PMID 41311552, 2025). "Cytokines play a pivotal role in host defense during sepsis, with key mediators such as tumor necrosis factor-α (TNF-α), interleukin (IL)-1, IL-6, and IL-10 implicated in its pathophysiology." (PMID 40944015, 2025). "Organ dysfunction in sepsis is often associated with elevated levels of cytokines such as IL-1β, IL-6, and TNF-α and activation of nuclear factor kappa B (NF-κB) pathways." (PMID 40896042, 2025). "Several studies have identified genetic variations associated with increased sepsis risk, such as polymorphisms in genes like tumor necrosis factor (TNF), suggesting potential applications for identifying high-risk patients." (PMID 39130839, 2024). "This combined treatment brought both IL-1β and TNF-α levels down to near-control values, underlining the synergistic potential of Vit C and CoQ10 in mitigating the inflammatory response in sepsis-induced cardiac injury." (PMID 38326366, 2024). "Study found that cytokines such as CCL2/MCP‐1, IL‐10, IL‐2, and TNF‐alpha were associated with lymphocyte morphology changes and other laboratory test results related to inflammation in sepsis, and those parameters were decreased in sepsis recovery." (PMID 39305165, 2024). "In a study of sepsis-associated acute lung injury, the exosome TNF-Exo promotes M1-type macrophage polarization while also initiating macrophage pyroptosis." (PMID 38178669, 2024). "Enhanced levels of IL-17 and of activation of its receptor also induce microglia activation and neuroinflammation, with increased TNFα and IL-1β brain levels, in a mice model of sepsis-associated encephalopathy." (PMID 38671534, 2024). "For instance, in a mouse model of Streptococcus pneumoniae sepsis, it was observed that administering oral antibiotics prior to the onset of sepsis was associated with decreased levels of TNF-α (a pro-inflammatory cytokine) in the lungs." (PMID 38361921, 2024). "Several studies have implicated single nucleotide polymorphisms of the TNF coding sequence as a potential protective factor against severe sepsis." (PMID 39469706, 2024). "A study examining how NAC treatment affects changes induced by sepsis in conscious rats revealed a reduction in inflammatory biomarkers (IL-6, tumor necrosis factor-α (TNF-α), and IL-10) linked to sepsis." (PMID 39064168, 2024).
Sepsis (continued). "In sepsis, bacterial infection induces the excessive release of inflammatory cytokines, such as tumor necrosis factor (TNF)-α, interleukin (IL)-1, and IL-18, causing cellular injury and multiple-organ dysfunction syndrome." (PMID 38584827, 2024). "According to earlier studies, RIPK3 protects mice against SIRS induced by TNF and sepsis caused by cecal ligation and puncture (CLP)." (PMID 38684668, 2024). "Sepsis is associated with high levels of inflammatory cytokines such as TNF-α, IL-1β, IL-6, and IL-10." (PMID 39597952, 2024). "Tumor necrosis factor-α (TNF-α) plays a key role in systemic inflammatory response by releasing other cytokines in sepsis, and the plasma levels of TNF-α are associated with sepsis-induced death." (PMID 39134731, 2024). "TNF-α plays a key role in the body’s immune response by regulating immune cells, inducing fever, causing apoptotic cell death, sepsis, and inflammation, and inhibiting tumorigenesis and viral replication." (PMID 38920613, 2024). "This led to higher production of TNF-α and IL-6, resulting in increased susceptibility to sepsis induced by methicillin-resistant Staphylococcus aureus (MRSA) infection." (PMID 38678059, 2024). "Previous studies have demonstrated the inhibitory effect of insulin on the release of sepsis-associated cytokines, including IL-1, IL-6, and TNF-α." (PMID 39263577, 2024). "In the early stages of sepsis, M1-like macrophages can be activated by individual Th1 cytokines (TNF-α and IFN-γ) or pathogen-associated molecular patterns (such as LPS)." (PMID 39252831, 2024). "Many immunomodulatory drugs, including IL-1 receptor antagonists and anti-TNF antibodies, have failed in human trials, which has caused a reevaluation of the existing strategies for developing drugs for sepsis." (PMID 39189251, 2024). "Blocking SEMA3A in sepsis led to a decreased secretion of TNF-α and IL-6, which was associated with lower mice mortality." (PMID 39770766, 2024). "Early repetitive or chronic RIC administration has shown benefits in reducing levels of inflammatory cytokines (such as TNF-α, IL-1β, and IL-6) following lipopolysaccharide-induced sepsis and has been associated with a reduction in mortality in mice." (PMID 36445625, 2024). "In HIV patients, elevated cytokine levels of interleukin (IL)-1, IL-6, IL-10, and tumor necrosis factor (TNF) are associated with the pathogenesis of sepsis in acute cases." (PMID 39676169, 2024). "Our findings are also consistent with an Australian study, they documented that preoperative administration of Dex in patients of delirium suppressed the TNF production and the release of mediators causing inflammation or sepsis." (PMID 39416599, 2024). "In acute stage of sepsis, the hyper-activated immune response including the increased IL-6, IL-1β and TNFα, as well as immune cell infiltration are the major causes for the multiple organ damages." (PMID 39726718, 2024). "There has been significant progress in understanding the mechanism by which TNF causes sepsis, focusing on its ability to induce oxidative damage, abnormal calcium distribution in cells, and activation of caspases." (PMID 39252831, 2024). "Oxidative stress activates the inflammatory response, and the release of pro‐inflammatory factors TNF‐α and IL‐1β causes alterations in sepsis‐induced cognitive abilities." (PMID 39508266, 2024). "In early phases of acute lung injury, a common risk factor of sepsis and lung infections, excessive airway fluid contains high concentrations of pro-inflammatory Th1 cytokines like TNF-α, TGF-β1, and IFN-γ, that are known to trigger ENaC dysfunction." (PMID 39052685, 2024). "Sepsis causes immune cells to release cytokines such TNF-α, IL-1, and IL-6, resulting in systemic inflammation." (PMID 39735547, 2024). "Another study found that polymorphisms in genes resulting in high TNF‐α and low IL‐10 production were associated with higher rates of sepsis in patients with AH." (PMID 37125245, 2023).
Sepsis (continued). "The inflammatory markers IL-6, IL-10, and TNF-α are all strongly linked to the onset of sepsis, and as one of the most important inflammatory cytokines, TNF-α stimulates the production of IL-6 in endothelial cells." (PMID 36644442, 2023). "TNF-α has been found to induce hepatocyte apoptosis, and its receptor plays a crucial role in liver injury caused by hepatotoxic drugs and sepsis, according to previous studies." (PMID 37916984, 2023). "Recent studies suggested that TNF-α (−238 G/A) polymorphism was associated with the progression of sepsis." (PMID 37388447, 2023). "Elevated ratios of anti-inflammatory to pro-inflammatory cytokines (e.g. IL10/TNF) are proposed markers of sepsis-induced immunosuppression, and are associated with multiple organ failure and increasing sepsis severity and mortality." (PMID 37033939, 2023). "Immune cell activation via LPS from the cell wall of infecting bacteria during sepsis can cause the production of inflammatory cytokines such as IL-6, IL-1β, and TNF-α." (PMID 37761018, 2023). "TNF-α is a vital pro-inflammatory cell cytokine that can trigger inflammatory cascades and cause multiple clinical symptoms in patients with sepsis, such as hypotension, disseminated intravascular coagulation, and organ failure." (PMID 37388447, 2023). "PKM2 is an important regulator of HMGB1 secretion, and this danger/damage-associated molecular pattern, secreted together with TNFα, has been associated with inflammatory macrophages and can cause lethal sepsis." (PMID 37475858, 2023). "In early sepsis, TNF-α causes t-PA to be released from endothelial cells and activates the fibrinolytic system." (PMID 37753078, 2023). "An increase in blood TNF-α levels raises the risk of pulmonary disease and rheumatic arthritis, cardiac insufficiency, leukemia, and sepsis." (PMID 37895334, 2023). "Several studies have reported an association between TNF-α and sepsis, reporting that an overexpression of TNF-α leads to poorer outcomes." (PMID 37630611, 2023). "In preclinical studies, IL-6 production and concomitant TNF-suppression have also been linked to the sepsis-typical co-stimulation of endosomal and cell surface toll-like receptors." (PMID 37869001, 2023). "Conversely, men predominantly display Th1 responses and overproduce TNF-α, IL-1β, IL-2, IL-6, and IL-8, which in turn is often associated with poor outcomes, such as septicaemia and bacteremia." (PMID 37004108, 2023). "TNFα blockade prevents the most significant events associated with sepsis, including systemic inflammation, septic shock, metabolic acidosis, and kidney injury." (PMID 37520526, 2023). "In sepsis, infection first causes increased secretion of core pro-inflammatory factors such as TNF-α and IL-1β." (PMID 37636994, 2023). "Sepsis is an important cause of cytokine storm, involving increased TNF, IL-1β, and IL-6 production through proinflammatory cells and sepsis pathology." (PMID 37108210, 2023). "Among them, TNF-α is an important promoter of sepsis and sepsis associated ALI, inducing the production of pro-inflammatory factors such as IL-6 and IL-8 and is an important systemic reactive mediator." (PMID 38076268, 2023). "IL-6 release generally follows that of TNF-α and is also an important inflammatory cytokine; several studies have shown that higher plasma levels of IL-6 are more likely to cause sepsis patients to die faster." (PMID 36675101, 2023). "The TNF (rs1800629) A allele was positively correlated with sepsis in CAP patients, with β = 1.81, OR = 6.14, p value= 0.027." (PMID 37630611, 2023). "It was found that the G/A gene polymorphism of TNF-α-308 is significantly positively associated with a higher incidence of sepsis and increased expression of cytokines such as TNF-α, IL-6, and IL-8 in patients." (PMID 37753078, 2023). "Sepsis is also associated with increased degradation of the glycocalyx, and a TNFα-induced increase in endothelial expression of heparinase is important for this degradation." (PMID 37048076, 2023).